RNVU1-6 (RNA, variant U1 small nuclear 6)
Synonyms: vU1.6; RNU1-99
Gene: Small nuclear RNA gene on chromosome 1 (146,052,081 to 146,052,244, reverse strand). Ensembl gene ENSG00000201558.
Gene Ontology:
Molecular function: pre-mRNA 5'-splice site binding
Biological process: mRNA 5'-splice site recognition
Cellular component: U1 snRNP
Homologues: Orthologues: chimpanzee U1 (93% identical), dog U1 (72% identical). Paralogues in human: RNU1-1 (91% identical), RNU1-2 (91% identical), RNU1-27P (91% identical), RNU1-28P (91% identical), RNU1-3 (91% identical), RNU1-4 (91% identical), RNVU1-18 (91% identical), RNVU1-29 (91% identical), RNVU1-31 (91% identical), U1 (91% identical), RNVU1-28 (90% identical), RNVU1-7 (90% identical), and 134 more.